EBLN1 (endogenous Bornavirus like nucleoprotein 1)
Description:
May act as an RNA-binding protein. Highly homologous to the bornavirus nucleocapsid N protein that binds viral RNA and oligomerizes (By similarity).
Synonyms: EBLN-1
Tractability: No criterion of Open Targets' tractability assessment is met for any kind of drug.
Gene: Protein-coding gene on chromosome 10 (22,208,475 to 22,218,018, reverse strand). Ensembl gene ENSG00000223601.
Genetic constraint (gnomAD): Loss-of-function variants: 4 observed, 3.11 expected, observed/expected ratio (o/e) 1.29, 90% interval 0.58 to 1.91. That is too few expected variants to judge how well the gene tolerates losing a copy. Missense variants: 389 observed, 392.14 expected, observed/expected ratio (o/e) 0.99, 90% interval 0.91 to 1.08. Synonymous variants: 153 observed, 144.93 expected, observed/expected ratio (o/e) 1.06, 90% interval 0.93 to 1.21.
Homologues: Orthologues: chimpanzee EBLN1 (97% identical). Paralogues in human: EBLN2 (45% identical).
Diseases named in the same sentence as EBLN1 in open-access papers:
EBLN1 is named in the same sentence as 7 diseases in open-access papers, as found by Europe PMC text mining. Sharing a sentence is not in itself a finding about the gene and the disease. The quoted sentences say what the papers report.
glioblastoma (1 paper, 2016). The most malignant astrocytic tumor (WHO grade IV). "Unlike with glioblastoma, OSRM was upregulated after EBLN1 silencing in OL cells." (PMID 27023521, 2016).
glioma (1 paper, 2016). A benign or malignant brain and spinal cord tumor that arises from glial cells (astrocytes, oligodendrocytes, ependymal cells). "Three genes closely related to glioma, RND3, OSMR, and CREB3L2, were significantly upregulated and might be the key factors in EBLN1 regulating the proliferation and apoptosis of OL cells." (PMID 27023521, 2016).
lentivirus infection (1 paper, 2016). Virus diseases caused by the Lentivirus genus. "At 4 days after lentivirus infection, when the expression of EBLN1 was reduced by 81%, wound-scratch assays were performed to test cell migration capability." (PMID 27023521, 2016). "The results displayed that EBLN1 silencing increased apoptosis, which was consistent with our results that the inhibit efficiency of LV-EBLN1-shRNA reached over 80% after a 96-h lentivirus infection, and the cell growth of EBLN1 silencing OL cells was decreased at 4 days post-infection." (PMID 27023521, 2016).
viral infection (1 paper, 2016). "Previous work has suggested that the bornavirus N gene (BDV N), from which human EBLN1 is derived, interacts with Cyclin B1-CDK1 complex within mammalian cells, which may be important for viral infection and propagation." (PMID 27739501, 2016).
cancer (2 papers, 2016). A tumor composed of atypical neoplastic, often pleomorphic cells that invade other tissues. "Analysis of the current Cancer Genome Atlas reveals that although no EBLN1 mutations have so far been identified in human tumours, a small percentage of tumour types exhibit EBLN1 amplification or deletion." (PMID 27739501, 2016). "Seeing that HERVs are involved in some human diseases, including cancers, such as endogenous retroviral LTR, K, and Fc-1, here we investigated the biological functions of EBLN1 in human OL cells." (PMID 27023521, 2016).
infection (1 paper, 2016). The state of being infected such as from the introduction of a foreign agent such as serum, vaccine, antigenic substance or organism. "Compared to the negative control, LV-EBLN1-shRNA1 lentiviral vectors could most efficiently reduce the expression of EBLN1 mRNA in OL cells by 81% after a 96-h infection." (PMID 27023521, 2016).
EBLN1 also shares sentences with these, for which no sentence is quoted: tumour (1 paper).